KRTAP19-1 (keratin associated protein 19-1)
Description:
In the hair cortex, hair keratin intermediate filaments are embedded in an interfilamentous matrix, consisting of hair keratin-associated proteins (KRTAP), which are essential for the formation of a rigid and resistant hair shaft through their extensive disulfide bond cross-linking with abundant cysteine residues of hair keratins. The matrix proteins include the high-sulfur and high-glycine-tyrosine keratins.
Synonyms: KAP19.1
Tractability: No criterion of Open Targets' tractability assessment is met for any kind of drug.
Gene: Protein-coding gene on chromosome 21 (30,479,706 to 30,480,367, reverse strand). Ensembl gene ENSG00000184351.
Pathways (Reactome):
Developmental Biology: Keratinization
Gene Ontology:
Molecular function: protein binding
Cellular component: cytosol
Genetic constraint (gnomAD): Loss-of-function variants: 4 observed, 1.94 expected, observed/expected ratio (o/e) 2.07. That is too few expected variants to judge how well the gene tolerates losing a copy. Missense variants: 116 observed, 118.98 expected, observed/expected ratio (o/e) 0.97, 90% interval 0.84 to 1.14. Synonymous variants: 45 observed, 49.03 expected, observed/expected ratio (o/e) 0.92, 90% interval 0.72 to 1.18.
Homologues: Orthologues: chimpanzee KRTAP19-1 (96% identical).
Diseases named in the same sentence as KRTAP19-1 in open-access papers:
KRTAP19-1 is named in the same sentence as 1 disease in open-access papers, as found by Europe PMC text mining. Sharing a sentence is not in itself a finding about the gene and the disease. The quoted sentences say what the papers report.
cancer (1 paper, 2022). A tumor composed of atypical neoplastic, often pleomorphic cells that invade other tissues. "Genes such FAM182A, SOX9, AHNAK2, ENSG00000121031, FLT3LG, PMEPA1, ZFP36L2 in the large intestine, ALB, KRTAP19-1, APOB, CD200, CRYGD, KRTAP24-1, OR6N2 in the liver are novel predictions, and their functions in these cancers can further be studied." (PMID 34997044, 2022).